UBA2 (ubiquitin like modifier activating enzyme 2)
Description:
The heterodimer acts as an E1 ligase for SUMO1, SUMO2, SUMO3, and probably SUMO4. It mediates ATP-dependent activation of SUMO proteins followed by formation of a thioester bond between a SUMO protein and a conserved active site cysteine residue on UBA2/SAE2.
Synonyms: SAE2; HRIHFB2115; FLJ13058; ACCES; ARX
Tractability: Small molecule: a structure with a bound ligand is known; a high-quality ligand is known; it has a high-quality binding pocket; it belongs to a druggable protein family. PROTAC: UniProt records ubiquitination sites on it; ubiquitination databases record sites on it; its protein half-life has been measured; a small molecule that binds it is known.
Target class: Enzyme; Aminoacyltransferase
Chemical probes: Subasumstat (high quality)
Gene: Protein-coding gene on chromosome 19 (34,428,352 to 34,471,251, forward strand). Ensembl gene ENSG00000126261.
Subcellular location: Cytoplasm; Nucleus
Subcellular location (Human Protein Atlas): Nucleoplasm
Pathways (Reactome):
Metabolism of proteins: SUMO is conjugated to E1 (UBA2:SAE1); SUMO is transferred from E1 to E2 (UBE2I, UBC9)
Gene Ontology:
Molecular function: ATP binding; magnesium ion binding; protein binding; protein heterodimerization activity; small protein activating enzyme binding; SUMO activating enzyme activity; SUMO binding; ubiquitin-like protein conjugating enzyme binding; ubiquitin-like modifier activating enzyme activity
Biological process: positive regulation of protein sumoylation; protein sumoylation; protein modification by small protein conjugation
Cellular component: nucleoplasm; SUMO activating enzyme complex; cytoplasm; nucleus
Genetic constraint (gnomAD): Loss-of-function variants: 6 observed, 45.94 expected, observed/expected ratio (o/e) 0.13, 90% interval 0.071 to 0.26. The upper end of that interval is the gene's LOEUF score, 0.26, which puts it in group 1 of 6, group 1 being the genes least tolerant of losing a copy. Missense variants: 389 observed, 631.43 expected, observed/expected ratio (o/e) 0.62, 90% interval 0.57 to 0.67. Synonymous variants: 246 observed, 231.6 expected, observed/expected ratio (o/e) 1.06, 90% interval 0.96 to 1.18.
Gene-disease validity (ClinGen):
ClinGen rates the evidence that UBA2 causes each of these diseases.
ACCES syndrome (autosomal dominant): Definitive. A rare congenital disease caused by a mutation in the UBA2 gene, charcterized by scalp defects, digital and skeletal anomalies, early growth deficiency, and neurodevelopmental delay.
Homologues: Orthologues: chimpanzee UBA2 (100% identical), macaque UBA2 (99% identical), guinea pig UBA2 (98% identical), rabbit UBA2 (97% identical), mouse Uba2 (94% identical), dog UBA2 (90% identical), rat Uba2 (88% identical), tropical clawed frog uba2 (80% identical), zebrafish uba2 (76% identical), Drosophila melanogaster Uba2 (51% identical), Caenorhabditis elegans uba-2 (41% identical). Paralogues in human: UBA6 (24% identical), UBA1 (24% identical), UBA3 (24% identical), UBA7 (23% identical), MOCS3 (11% identical), UBA5 (9% identical), ATG7 (7% identical), NAE1 (6% identical), SAE1 (5% identical).
Diseases named in the same sentence as UBA2 in open-access papers:
UBA2 is named in the same sentence as 36 diseases in open-access papers, as found by Europe PMC text mining. Sharing a sentence is not in itself a finding about the gene and the disease. The quoted sentences say what the papers report.
colorectal cancer (9 papers, 2019 to 2023). A primary or metastatic malignant neoplasm that affects the colon or rectum. "In colorectal cancer, high UBA2 expression is positively correlated with EZH2 expression and unfavorable prognosis of patients." (PMID 37777749, 2023). "He at al. observed a significant increase in the gene and protein expression of UBA2 in colorectal cancer samples when compared with control samples, identifying overexpression of this gene as an adverse prognostic marker." (PMID 35992817, 2022). "Inhibition of UBA2 expression reduces the proliferation of colorectal cancer and gastric cancer cells regulating cyclinB1, B cell lymphoma-2, and E3 ubiquitin-protein ligase MDM2." (PMID 33008487, 2020). "In fact, SUMO was described to be indispensable for cancer cell proliferation and an siRNA-mediated knockdown of UBA2 was shown to inhibit colorectal cancer cell invasion and migration by downregulation of the Wnt/β-catenin signaling pathway." (PMID 31575873, 2019). "Interestingly, UBA2 plays a vital role in multiple diseases, such as colorectal cancer 30, breast cancer 32, and lung cancer." (PMID 37056932, 2023). "The SH3PXD2A-AS1/miR-330-5p/UBA2 network may influence colorectal cancer growth via the Wnt/-catenin pathway." (PMID 35573701, 2022). "In addition, UBA2 can promote the progression of colorectal cancer and is expected to become a potential therapeutic target for colorectal cancer." (PMID 34267779, 2021). "Recently, it was demonstrated that UBA2 is highly expressed in a variety of cancers, including liver cancer, NSCLC, gastric cancer, and colorectal cancer." (PMID 34930905, 2021).
breast carcinoma (6 papers, 2019 to 2023). "The first links between SUMO and Myc were obtained in breast cancer model cell lines where overexpression of Myc was shown to be synthetic lethal with the loss of Uba2/Aos1 SUMO E1 and Ubc9 SUMO E2 activity." (PMID 31405039, 2019). "In addition, UBA2 has been reported to promote the progression of colon cancer, liver cancer, breast cancer, and other tumors." (PMID 35606717, 2022). "For instance, high SAE1 and UBA2 (SAE2) levels are correlated with decreased survival and increased metastatic ability in patients with breast cancer." (PMID 32938830, 2020).
gastric cancer (4 papers, 2020 to 2021). A primary or metastatic malignant neoplasm involving the stomach. "For example, ubiquitin-like modifier activating enzyme 2 (UBA2) induces the migration and invasion of gastric cancer cells." (PMID 33344241, 2020).
hepatocellular carcinoma (3 papers, 2014 to 2023). A malignant tumor that arises from hepatocytes. "Overexpression of SUMO-2 and the Uba2 E1 subunit has been correlated with poor survival of hepatocellular carcinoma patients." (PMID 24971752, 2014). "Luteolin can regulate the mRNA expression of pro-proliferative genes, pro-apoptotic genes, and angiogenic molecules Uba2, VEGF, Fra-1, HIF-1α, and Rac1 in hepatocellular carcinoma HepG2 cells, thereby inhibiting the proliferative activity and angiogenesis of hepatocellular carcinoma cells." (PMID 37151401, 2023).
lung carcinoma (3 papers, 2021 to 2024). "For example, UBA2 was highly expressed in lung cancer and it knockdown increased the sensitivity of cancer cell to etoposide and cisplatin." (PMID 39211047, 2024).
clear cell renal cell carcinoma (2 papers, 2021 to 2023). "UBA2-KD promotes the apoptosis of clear cell renal cell carcinoma cells." (PMID 37056932, 2023). "Ubiquitin-like modifier-activating enzyme 2 (UBA2) is an important member of the SUMO modification system; however, its role in clear cell renal cell carcinoma (ccRCC) is unclear." (PMID 34753901, 2021).
Ectrodactyly (2 papers, 2021 to 2024). A condition in which middle parts of the hands and/or feet (digits and meta-carpals and -tarsals) are missing giving a cleft appearance. "In addition, it enabled the identification of three candidate genes and the independent verification of the novel disease gene UBA2 for causing ectrodactyly." (PMID 34159400, 2021). "Interestingly, PHIP and UBA2, which have been associated with similar disease profiles of oligodactyly and ectrodactyly, respectively, also showed similar temporal expression patterns in mesenchymal-chondrocytes, -fibroblasts, ectodermal-sost, and muscle cells." (PMID 38228144, 2024).
glioblastoma (2 papers, 2021 to 2025). The most malignant astrocytic tumor (WHO grade IV). "As can be seen from the figure, UBE2I, UBA2, PIAS3, and SENP1 were upregulated in glioblastoma, whereas PIAS1, RANBP2, SENP5, and SENP2 were downregulated in glioblastoma." (PMID 33898460, 2021). "Moreover, UBE2I, UBA2, PIAS3, and SENP1 were highly expressed in glioblastoma, whereas PIAS1, RANBP2, SENP5, and SENP2 were downregulated in glioblastoma." (PMID 33898460, 2021). "UBE2I, UBA2, PIAS3, and SENP1 were highly expressed in glioblastoma." (PMID 33898460, 2021).
glioma (2 papers, 2023 to 2025). A benign or malignant brain and spinal cord tumor that arises from glial cells (astrocytes, oligodendrocytes, ependymal cells). "Interestingly, some of these genes, e.g., LRRC41 and UBA2, have been identified previously as being related to tumor progression, cell cycle and ubiquitination pathways, and altered expression of these genes could be a cause of glioma pathogenesis." (PMID 41300918, 2025). "The GEPIA database predicted a positive correlation between UBA2 expression and survival time in patients with glioma." (PMID 37906341, 2023). "The increased UBA2 expression in glioma cells promoted RALY SUMOylation, which, in turn, upregulated the expression of RALY by increasing its stability." (PMID 37906341, 2023). "Compared with non-tumorous brain tissues (NBTs), glioma tissues exhibited an increased UBA2 expression, with U251 and U373 glioma cells showing higher levels than normal HA cells." (PMID 37906341, 2023). "Our data suggested that UBA2 is increased in gliomas, and its knockdown impedes cell migration, invasion, and VM." (PMID 37906341, 2023). "Therefore, although the role of UBA2 in glioma is corroborated by new empirical evidence, the role that LRRC41 plays in glioma is more hypothetical and should be further functionalized." (PMID 41300918, 2025). "In addition, SUMOylation by UBA2 is also operative in glioma: UBA2 and its target RALY are increased in glioma cells and UBA2 knockdown inhibits vasculogenic mimicry and glioma cell proliferation." (PMID 41300918, 2025). "Knockdown of UBA2 impeded the malignant progression of glioma cells." (PMID 37906341, 2023). "In this study, we discovered that UBA2 demonstrated elevated expression levels in glioma." (PMID 37906341, 2023). "We detected the expression of UBA2 in glioma tissues and cells by Western blot." (PMID 37906341, 2023). "Furthermore, the overexpression of RALY facilitated the migration, invasion, and vasculogenic mimicry of glioma cells and, more importantly, rescued the suppression of migration, invasion, and VM induced by UBA2 knockdown." (PMID 37906341, 2023). "Similar to the results of these studies, UBA2 demonstrated oncogenic activity in glioma cells." (PMID 37906341, 2023). "Moreover, UBA2 inhibition significantly inhibited VM in glioma cells." (PMID 37906341, 2023). "This study revealed that the expression levels of UBA2 and RALY in glioma cells and tissues are significantly increased, and RALY can be modified by SUMO1 in glioma." (PMID 37906341, 2023). "The combined inhibition of UBA2, RALY, and FOXD1 significantly impeded glioma cell migration, invasion, and VM compared with the control group." (PMID 37906341, 2023). "In the present study, we found that UBA2 and RALY were upregulated in glioma tissues and cell lines." (PMID 37906341, 2023). "In this study, we found that the expression levels of UBA2, RALY, FOXD1, and DKK1 were significantly increased in glioma cells and tissues and were negatively correlated with the overall survival time in glioma patients." (PMID 37906341, 2023). "Interactions among UBA2, RALY, FOXD1, and DKK1 play an important role in regulating migration, invasion, and vasculogenic mimicry in glioma cells." (PMID 37906341, 2023). "Downregulation of UBA2 and RALY inhibited the migration, invasion, and VM of glioma cells." (PMID 37906341, 2023). "In addition, we found that the inhibition of UBA2, RALY, FOXD1, and DKK1 inhibited glioma cell migration, invasion, and vasculogenic mimicry." (PMID 37906341, 2023). "In addition, we profiled the expression of UBA2, RALY, FOXD1, and DKK1 and explored the probable interaction mechanism among these molecules in the regulation of vasculogenic mimicry (VM) in glioma." (PMID 37906341, 2023). "The inhibitor of UBA2, RALY, FOXD1, and DKK1 may serve as the therapeutic target in glioma." (PMID 37906341, 2023).
glioma (continued). "UBA2/RALY/FOXD1/DKK1 axis may play crucial roles in regulating VM in glioma, which may contribute to the development of potential strategies for the treatment of gliomas." (PMID 37906341, 2023).
leukemia (2 papers, 2023 to 2024). A malignant (clonal) hematologic disorder, involving hematopoietic stem cells and characterized by the presence of primitive or atypical myeloid or lymphoid cells in the bone marrow and the blood. "A recent study further showed that a frameshift variant of UBA2 was discussed to predispose to ETV6::RUNX1+ leukemia in monozygotic twins." (PMID 37469802, 2023). "Our research team is dedicated to studying leukemia drivers and has identified the UBA2-WTIP fusion gene as a key target." (PMID 39496012, 2024).
lung adenocarcinoma (2 papers, 2023 to 2024). A carcinoma that arises from the lung and is characterized by the presence of malignant glandular epithelial cells. "Therefore, we focused on the role of UBA2 in lung adenocarcinoma (LUAD) and its association with patient prognosis." (PMID 38407971, 2024).
non-small cell lung carcinoma (2 papers, 2022). A group of at least three distinct histological types of lung cancer, including non-small cell squamous cell carcinoma, adenocarcinoma, and large cell carcinoma. "Finally, the results of the CCK-8 assay, cell cycle analysis, and transwell assay demonstrated that the two risk genes, SAE1 and UBA2, could promote proliferation and migration in non-small cell lung cancer cells." (PMID 35606717, 2022).
Arthritis (1 paper, 2020). Inflammation of a joint. "Since SAE1/UBA2 function is predominately dependent on TNF-α–induced activation in vitro, we also determined the effect of GA on joint inflammation in TgTC mice, a human TNF-α transgenic model of arthritis." (PMID 32938830, 2020).
HIV-1 infection (1 paper, 2008). The type species of lentivirus and the etiologic agent of acquired immunodeficiency syndrome (AIDS). "In this pilot study, we tested whether APOBEC3G, when it is fused with UBA2, can resist Vif-mediated proteasomal degradation and further inhibit HIV-1 infection." (PMID 18680593, 2008).
melanoma (1 paper, 2022). A malignant, usually aggressive tumor composed of atypical, neoplastic melanocytes. "Moreover, MYC and UBA2 expression was inversely correlated with the presence of CD8+ T cells in patients with melanoma, which is a predictive biomarker for the success of ICB." (PMID 35499080, 2022).
osteosarcoma (1 paper, 2015). A usually aggressive malignant bone-forming mesenchymal neoplasm, predominantly affecting adolescents and young adults. "Downregulation of miR-143 promotes osteosarcoma cell invasion through MMP-13 upregulation, and silencing of miR-133a reduces the malignancy of CD133high osteosarcoma-initiating cell population through restoring the expression of multiple target genes (SGMS2, UBA2, SNX30, and ANXA2)." (PMID 25912304, 2015).
ovarian carcinoma (1 paper, 2022). A malignant neoplasm originating from the surface ovarian epithelium. "Thus, it seems that screening diagnosis of ovarian cancer should be supplemented by GLO1, TUFT1, and UBA2 determination and assessment of the risk of loss of adequate response to chemotherapy by GLO1 mRNA expression pattern determination." (PMID 35992817, 2022). "In our analysis, we demonstrated overexpression of UBA2 mRNA, and the protein coded by it in ovarian cancer samples (p < 0.05), it was higher in group A where surgical treatment was complemented by chemotherapy when compared with group B where treatment was terminated by surgery." (PMID 35992817, 2022). "We noted that the mRNA of UBA2, GLO1, TUFT1, HPD, and GBF1 were upregulated in the ovarian cancer samples in comparison to the control samples." (PMID 35992817, 2022). "mRNAs corresponding to genes UBA2, GLO1, STATH, and TUFT1, were differentiated in the study samples, irrespective of the stage of ovarian cancer from the control samples, and we decided to focus on them in further analyses." (PMID 35992817, 2022).
renal cell carcinoma (1 paper, 2023). "In renal cell carcinoma, significantly increased UBA2 expression is related to higher stages and poorer prognosis." (PMID 37906341, 2023).
rheumatoid arthritis (1 paper, 2024). A chronic, systemic autoimmune disorder characterized by inflammation in the synovial membranes and articular surfaces. "SUMOylation is involved in glycolytic metabolism, and UBA2 knockdown inhibits SUMO protein activation and maintains high PK activity, thereby reducing glycolytic metabolism in rheumatoid arthritis." (PMID 39368995, 2024).